IL1B (interleukin 1 beta)
Diseases named in the same sentence as IL1B in open-access papers (continued):
Sharing a sentence is not in itself a finding about the gene and the disease.
subarachnoid hemorrhage (22 papers, 2016 to 2025). A serious neurological disorder characterized by intracranial hemorrhage into the subarachnoid space. "By suppressing the activation of caspase-1 and preventing the assembly of the NLRP3 inflammasome, inhibiting P2X7R can reduce the production of IL-1β/IL-18 and lessen early brain damage in the subarachnoid hemorrhage model." (PMID 41383474, 2025). "Baicalin is further known to reduce the levels of AQP4, TNF-α, and IL-1β in rats with subarachnoid hemorrhage." (PMID 35764613, 2022). "Fluoxetine has neuroprotective effects by reducing the production of proinflammatory factors, including NO, TNF-α, iNOS, and IL-1β, in early brain injury after subarachnoid hemorrhage." (PMID 34899324, 2021). "The effects of ROF on cerebral inflammation developing in the subarachnoid hemorrhage model in rats were investigated and it was shown that it significantly reduced neurological damage and inflammatory cytokines IL1β, IL-6, and TNFα levels and the number of apoptotic neurons." (PMID 36865049, 2023). "Pro-inflammatory cytokines, such as IL-1β, IL-6, and tumor necrosis factor-α, which have been shown to be activated in POEMS syndrome, are reportedly associated with cerebral vasospasm after subarachnoid hemorrhage." (PMID 34167480, 2021). "For instance, MLT was also demonstrated to protect against brain damage induced by subarachnoid hemorrhage (SAH) via the suppression of NLRP3 inflammasome-related components, including ASC, cleaved Casp-1, IL-1β, and IL-669,70." (PMID 36747075, 2023). "Fan and colleagues reported that treatment with mdivi-1 decreased brain expression of IL-1β, TNF-ɑ, and IL-6 24 h after subarachnoid hemorrhage injury in rats." (PMID 33612100, 2021). "In a model of subarachnoid hemorrhage in rats, a very recent study found that AE1-329, an EP4 receptor agonist, significantly reduced BBB damage, edema, and expression of IL-1β, IL-6, and TNF-α." (PMID 29527151, 2018). "Real-time PCR data demonstrated that baicalin attenuated increased proinflammatory cytokine (IL-1β, IL-6, and CXCL-3) production in subarachnoid hemorrhage mice." (PMID 28912935, 2017).
atrial fibrillation (21 papers, 2010 to 2026). A disorder characterized by an electrocardiographic finding of a supraventricular arrhythmia characterized by the replacement of consistent P waves by rapid oscillations or fibrillatory waves that vary in size, shape and timing and are accompanied by an irregular ventricular response. "A study reported that TLR8 was correlated with levels of IL6, IL1β, and a greater inflammatory response, which is an important mechanism that causes atrial fibrillation." (PMID 36671813, 2023). "Furthermore, activation of the NLRP3 inflammasome in an atrial fibrillation rat model has been shown to be closely associated with elevated IL-1β expression in myocardial tissue." (PMID 41561130, 2025). "Some studies suggested that NAFLD might be a contributor of atrial fibrillation, and this finding was associated with macrophage-derived IL-1β." (PMID 38630423, 2024). "In addition, regional IL-1β in EAT was an independent risk factor for persistent atrial fibrillation." (PMID 36158806, 2022). "To clarify the correlation between inflammation and thrombosis in atrial fibrillation, we detected the mRNA expressions of classic inflammatory molecules (i.e., IL-1β, interleukin-1 beta; IL-6, interleukin 6; TNF-α, tumor necrosis factor-alpha)." (PMID 29595637, 2018). "Colchicine, a recognized anti-inflammatory agent, has demonstrated mechanistic effects in atrial fibrillation in animal studies, including inhibition of IL-6 release triggered by IL-1β, attenuation of subsequent atrial fibrosis, and modulation of ion channel gene expression and signaling pathways." (PMID 41608286, 2026). "Notably, fibroblast-restricted NLRP3 activation has been shown to promote atrial fibrillation and diastolic dysfunction via increased IL-1β secretion and intercellular crosstalk with cardiomyocytes, culminating in electrical remodeling and calcium mishandling." (PMID 40649732, 2025). "In C57BL/6 mice, IL-1β inhibits QKI expression in cardiomyocytes, reducing the mRNA stability of CACNA1C, leading to downregulation of ICa-L, and inducing electrical remodeling and increased susceptibility to atrial fibrillation." (PMID 41561130, 2025). "The factors they secrete, such as IL-1β and TGF-β, drive the electrophysiological remodeling of cardiomyocytes and the activation of cardiac fibroblasts, leading to structural and functional abnormalities associated with atrial fibrillation." (PMID 41561130, 2025). "Additionally, spatial transcriptomics revealed that the IL-1β signaling axis in atrial fibrillation tissue exhibits a band-like distribution along the atrial posterior wall and pulmonary vein entrance regions." (PMID 41561130, 2025). "The increased mRNA expressions of classic inflammatory factors (i.e., interleukin-1 beta, interleukin 6, and tumor necrosis factor-alpha) in AF(+)thrombus(+) group further validated the correlation between inflammation and thrombi in atrial fibrillation." (PMID 29595637, 2018). "Elevated levels of CXCL8, CCL11, CCL2, CXCL10, IL-1β, IL-6, TNF-α, IFN-γ, IL-17, IL-1Ra, IL-4, IL-9, FGF-basic, PDGF, G-CSF, and GM-CSF were observed in the Atrial fibrillation patient, in contrast to uninfected controls." (PMID 29370812, 2018). "In particular, the infiltration of M1-type macrophages has been shown to significantly increase in persistent AF, accompanied by elevated levels of IL-1β and NLRP3 expression, suggesting that the activation of inflammatory pathways plays a key role in atrial fibrillation." (PMID 41561130, 2025). "Furthermore, increased levels of CCL5, IL-1β, TNF-α, IFN-γ, IL-9, G-CSF, and GM-CSF were observed only in the atrial fibrillation patient, when compared to other Zika patients." (PMID 29370812, 2018).
atrial fibrillation (continued). "M1 macrophages secrete pro-inflammatory factors (TNF-α, IL-1β, and IL-6) to induce cardiac electrical remodeling, in which IL-1β has been shown to reduce the expression of atrial tremor protein (QKI) and further attenuate L-type Ca2+ current in cardiocytes to inhibit atrial fibrillation." (PMID 39104386, 2024). "In general, the results revealed that the ZIKV-infected patient with atrial fibrillation presented a typical serum biomarker storm already reported for ZIKV-infected patients, with a more prominent pro-inflammatory status mediated by CCL5, IL-1β, TNF-α, and IFN-γ." (PMID 29370812, 2018).
bacterial meningitis (21 papers, 2007 to 2024). Inflammation of the membranes surrounding the brain and spinal cord due to a bacterial infection. "It has been revealed that CSF levels of inflammasome-associated cytokines IL-1β and IL-18 were increased in patients with bacterial meningitis, and that this was associated with complications and unfavorable outcomes." (PMID 35145923, 2021). "We studied associations between inflammasome-associated cytokines IL-1β and IL-18 in cerebrospinal fluid (CSF) of patients with bacterial meningitis and clinical outcome, and pneumococcal serotype." (PMID 23902681, 2013). "In patients with bacterial meningitis, CSF levels of inflammasome associated cytokines IL-1β and IL-18 were related to complications, and unfavorable disease outcome." (PMID 23902681, 2013). "It has been shown that IL-1β and IL-18 levels are upregulated during bacterial meningitis and, specifically, IL-1β levels are correlated with leukocyte levels in the CSF and neuronal sequelae in patients." (PMID 34149363, 2021). "Concentrations of IL-1β are elevated in CSF samples from patients with bacterial meningitis and correlate significantly with CSF leukocyte counts and clinical outcome." (PMID 28300164, 2017). "IL-1b was found in the CSF of human patients with bacterial meningitis and was the initial cytokine produced upon the induction of pneumococcal meningitis in a rat model." (PMID 28409125, 2017). "In this study we measured the CSF levels of inflammasome related cytokines IL-1β and IL-18 in a prospective nationwide cohort of community acquired bacterial meningitis and correlated these to clinical data and pneumococcal serotype." (PMID 23902681, 2013). "Cytokines and chemokines, including IL-8, IL-6, TNFα, MCP-1 and IL-1β, have been found in CSF during bacterial meningitis." (PMID 23448224, 2013). "In addition, the levels of several inflammatory cytokines, such as interleukin (IL)-6, tumor necrosis factor (TNF)-α, IL-1β, and IL-18, are increased in the cerebrospinal fluid (CSF) of patients affected by bacterial meningitis." (PMID 35145923, 2021). "Among them, IL-1β and IL-18 are the main downstream effectors of inflammasome activation, and therefore may also be involved in the neuroinflammatory response to bacterial meningitis." (PMID 35145923, 2021). "The ELISA quantification results (pg/mg protein) showed that intranasal administration of bacterial meningitis in rats significantly stimulated the pro-inflammatory cytokines production, TNF-α, IL-6 and IL-1β, compared with the controls." (PMID 36015052, 2022). "A variety of cytokines have been demonstrated in the CSF of patients with bacterial meningitis, including interleukin-6 (IL6), interleukin-8 (IL8), interleukin-1-beta (IL1b), and tumor necrosis factor alpha (TNFa)." (PMID 34680826, 2021). "In the pathogenesis of cerebral injury in bacterial meningitis, TNF-α, IL-6, and IL-1β are major early response cytokines that trigger, often in synergy, a cascade of inflammatory mediators, including other cytokines, oxygen intermediates, and chemokines." (PMID 34437417, 2021). "For the pathogenesis of bacterial meningitis, the cytokines and chemokines that are characteristically found in the CSF of patients, include IL6, IL8, TNFα, CXCL1 IL1β and MCP-1." (PMID 34863201, 2021). "Several proinflammatory cytokines were found to be upregulated such as IL-1β and TNF-α, supporting increased inflammation as observed in bacterial meningitis cases." (PMID 32529267, 2020). "Elevated IL-8, IL-1β, TNF-α, and IL-6 have routinely been shown to be elevated in bacterial meningitis." (PMID 30626412, 2019). "Additionally, pyroptosis causes the excessive production of cytokines and chemokines including TNF-α, IL-1β, IL-6, CCL3, CXCL-1, CXCL-2, etc. in bacterial meningitis which can also result in inflammatory mediator-induced neuronal damage." (PMID 26683708, 2015).
glomerulonephritis (21 papers, 2011 to 2025). A renal disorder characterized by damage in the glomeruli. "It is also observed clinically that NLRP3 inflammasomes are activated and mature IL-1β is released in anti-neutrophil cytoplasmic antibody-associated glomerulonephritis patients." (PMID 32660446, 2020). "Deficiency of IL-1β attenuates progression of mouse glomerulonephritis with less crescent formation, indicating the importance of IL-1β in the pathogenesis of CKD in mice." (PMID 32660446, 2020). "In an anti-GBM glomerulonephritis mouse model and IL-1β–induced MPC5 podocytes, ginsenoside Rg1 reduces inflammation and apoptosis via Nrf2 activation, an effect confirmed by the Nrf2 inhibitor ML385." (PMID 41415561, 2025). "Podocytes have been demonstrated to be the primary producers of IL-1α and IL-1β in humans and experimental models of glomerulonephritis." (PMID 38672094, 2024). "Several studies suggest the involvement of P2RX7 and IL‐1β in autoimmune and inflammatory diseases, including glomerulonephritis (GN), in both rodents and humans." (PMID 35239186, 2022). "Here, we also observed a statistically significant increase in IL-1β serum level of glomerulonephritis-HD patients which can further support the activation of the NLRP3-ASC-caspase-1 axis in these patients." (PMID 34904012, 2021). "Mature IL-1β secretion was quantified by ELISA in the serum of glomerulonephritis-HD patients, and the serum samples from healthy persons (n = 10) were used as controls." (PMID 34904012, 2021). "Compared to controls, an elevated serum level of IL-1β (4.58-fold increase) (p < 0.001) was observed in glomerulonephritis-HD patients." (PMID 34904012, 2021). "It is worth noting that podocytes are the major source of IL-1β during glomerulonephritis and a reduction in IL-1β could result in a glomeruloprotective effect." (PMID 33918778, 2021). "In both of these models, glomerulonephritis develops secondary to systemic immune complex disease, therefore, the role of intrarenal IL-1β and IL-18 production remains unclear." (PMID 22046355, 2011). "The present study confirmed the previous finding that IL-1β induces COX-2 expression and PGE2 production, suggesting that the COX-2–PGE2 pathway may mediate the pathological effect of IL-1β in human glomerular mesangial cells and in multiple types of glomerulonephritis." (PMID 35888719, 2022). "The production of IL-1β has been shown to play a critical role in the pathogenesis of ANCA vasculitis, with the IL-1 receptor antagonist anakinra protecting against glomerulonephritis in an anti-MPO-induced mouse model." (PMID 26149790, 2015). "Similar to IL-1β, evidence for renal expression of IL-1Ra in non-immune cells is restricted to glomerular detection in a rat glomerulonephritis model." (PMID 40486517, 2025). "Interleukin 1α and IL-1β are produced by both blood-borne immune cells as well as by intrinsic renal cells as it was observed in human proliferative and non-proliferative forms of glomerulonephritis where there was increased production of IL-1 in the podocytes." (PMID 32733443, 2020).
Kawasaki disease (21 papers, 2018 to 2026). A rare inflammatory disease characterized by an acute febrile, systemic, self-limiting, medium-vessel vasculitis primarily affecting children. "IL-1β has previously been reported to play a key role in the inflammatory profile of Kawasaki disease, and IL-2 is significantly higher in children with Kawasaki than in healthy controls." (PMID 37064248, 2023). "In a study on Kawasaki disease, elevated CRP was associated with elevated IL-6, elevated IL-1β, and subsequently rates of hyponatremia." (PMID 37744432, 2023). "Mice with Kawasaki’s disease, an inflammatory disease model, present impaired endothelium-dependent vasodilation accompanied by increased caspase-1, IL-1β, and VCAM-1 expression." (PMID 32009974, 2019). "Moreover, previous studies have provided strong evidence that IL-1β plays a pivotal role in the pathogenesis of coronary lesions in a mouse model of Kawasaki disease (KD), which can be effectively inhibited by IL-1 receptor antagonists." (PMID 40241989, 2025). "In addition, a recent report found that the Dectin-2/Syk/JNK/NF-κB pathway induces NLRP3 and pro-IL-1β expression in Kawasaki disease, which is similar to our conclusion." (PMID 34603335, 2021). "T cells further recruit immune cells to the vessel wall by secreting cytokines such as IL-1β, TNF-α and chemokines such as CCL2.In animal models, CD8+ T cells are essential for the development of vascular inflammation in Kawasaki disease." (PMID 40746545, 2025). "Enzyme-linked immunosorbent (ELISA) was used to detect serum levels of chemerin, omentin-1, adiponectin, and inflammatory cytokines IL-1β and TNF-α in 80 cases of patients diagnosed with Kawasaki disease (KD)." (PMID 29739418, 2018). "Our data are also consistent with in vivo observations wherein IVIg treatment reduces serum IL-6 and IL-6 production by LPS-stimulated whole blood in children with Kawasaki disease, and reduces serum TNF and IL-1β levels in patients with Guillain-Barré syndrome." (PMID 30515163, 2018).
osteomyelitis (21 papers, 2014 to 2024). An acute or chronic inflammation of the bone and its structures due to infection with pyogenic bacteria. "This suggests the need for a more nuanced examination of different osteomyelitis subtypes and an independent exploration of the relationships between IL-1β gene polymorphisms and these varying types of osteomyelitis." (PMID 39301021, 2024). "Pro-inflammatory cytokines such as IL1B and IL-6 are considered to be significant risk factors for osteomyelitis." (PMID 37904457, 2023). "We show that while deficiencies in components of Toll-like receptor signaling pathways do not affect CMO development, deficiency in CD45 phosphatase lowers IL-1β levels in Pstpip2cmo mice leading to mitigation of osteomyelitis and tissue inflammation." (PMID 34461100, 2021). "Osteomyelitis, in particular, is associated with abundant levels of pro-inflammatory cytokines such as TNFα, IL-1β, and IL-6." (PMID 30978245, 2019). "To determine the contribution of MyD88 and IL-1R signaling towards antibacterial immune responses during S. aureus osteomyelitis, we infected mice globally deficient in MyD88, IL-1R, IL-1α, and IL-1β and measured bacterial burdens and morbidity." (PMID 30978245, 2019). "Whether the NLRP3/IL-1β signaling pathway is involved in susceptibility to osteomyelitis due to NLRP3 polymorphism (rs10754558) is unclear." (PMID 39301021, 2024). "Furthermore, their study revealed that individuals harboring the IL1RN*2/*2 + IL1B-511T/T polymorphism genotype were all afflicted with osteomyelitis." (PMID 39301021, 2024). "Interleukin-1 beta gene polymorphism rs16944 may associate with increased susceptibility to extremity chronic osteomyelitis in Chinese Han population." (PMID 30949508, 2019). "In the case of osteomyelitis, key SNPs within genes such as IL-1β (including rs1143634 and rs16944), IL-6 (e.g., rs1800795), VDR, and TNF-α are instrumental in evaluating susceptibility." (PMID 39301021, 2024). "Further studies revealed that these gut microbiome alterations upregulate pro-IL-1β levels, suggesting that the gut microbiome can indirectly affect osteomyelitis via regulating pro-IL-1β levels in the circulatory system." (PMID 34434965, 2021). "Again, serine proteases from neutrophils drive the inflammation and production of mature IL-1β in a murine model of osteomyelitis." (PMID 30583612, 2018). "The increased expression of IL-1β and inflammasome-associated AIM2 as well as an implication of the Mitophagy pathway reported here supports the involvement of inflammasomes in the long-term infection leading to the development of osteomyelitis." (PMID 35531332, 2022). "Previous work has shown that IL-1β and IL-6 production is increased during osteomyelitis." (PMID 34484165, 2021). "More importantly, IL-1β, IFN-γ, and TNF-α were both elevated in osteomyelitis sera and their receptors in DFU." (PMID 37904457, 2023). "Among them, IL1B, IL-6, IL8, and MMPs may be involved in the common pathogenesis of silver DFU and osteomyelitis." (PMID 37904457, 2023). "In this respect, several preclinical and clinical observations indicate that osteomyelitis is accompanied by alterations in the local and (sometimes) systemic levels of both pro-inflammatory (e.g., IL-6, IL-1α, TNF-α, IL-1β) and anti-inflammatory (e.g., TGF-β1) cytokines." (PMID 36483565, 2022). "Osteomyelitis was an essential part of bone infection disease and characterized by a severe inflammatory reaction that contributed to bone destruction due to the release of pro-inflammatory cytokines (TNF-α, IL-1β and IL-6) from many bacterial." (PMID 32527985, 2020). "Therapeutically blocking the IL-1RI or IL-1β (n = 10), but not TNF (n = 4), results in prompt resolution of systemic inflammation and healing of the sterile osteomyelitis seen in Majeed syndrome patients." (PMID 33670882, 2021).